MPO (myeloperoxidase)
Diseases named in the same sentence as MPO in open-access papers (continued):
Sharing a sentence is not in itself a finding about the gene and the disease.
tumor (continued). "Overall, our findings support combination MPO inhibition and ICT as a new treatment approach for delaying PDAC tumor growth." (PMID 38367056, 2024). "Enhanced ICT response was observed, characterized by a significant delay in tumor growth and increased survival time, in ICT treated MPO−/− mice compared to WT mice." (PMID 38367056, 2024). "ADCC triggers the release of ROS in addition to other cytotoxic molecules such as lactoferrin, elastase, arginase, myeloperoxidase, cathepsins, defensins, and MMP9 to eliminate tumor cells." (PMID 37376417, 2023). "Other MPO inhibitors, such as verdiperstat and AZD5904, have been shown to be effective in mouse tumor models and should be used in future studies to evaluate the importance of MPO activity in trophoblast migration and invasion." (PMID 37776707, 2023). "Further supporting the role of MPO, the 3-IAA oxidation product MOI was increased in tumours from wild-type SPF mice after treatment with 3-IAA and FIRINOX compared to that with FIRINOX alone." (PMID 36813961, 2023). "In PC-3 tumor nodules harvested on day 8 after injection, the enhanced leukocyte infiltrate in ITGB4 KD tumors was again visible, characterized by arginase-1- and myeloperoxidase (MPO)-positive cells." (PMID 36932441, 2023). "More interestingly, myeloperoxidase (MPO) activity was boosted 10-fold in the TME after RT and the anti-tumor capacity of neutrophils was supported by high MPO activity." (PMID 37833255, 2023). "Tumor growth in HFD-fed obese mice had higher circulating dsDNA and citrullinated histone H3, plasma HMGB1, tumor contents of HMGB1, citrullinated histone H3, neutrophil elastase, PAD4 and MPO when compared to tumors in ND-fed lean mice." (PMID 36012397, 2022). "In the cancer microenvironment, tumor-associated neutrophils (TANs) secret various cytokines and metabolic products (myeloperoxidase—MPO), therefore they influence the recruitment of monocytes and macrophages, providing them with pro- or anti-tumor functions." (PMID 35741450, 2022). "We also determined the lineage contribution of the tumor cells by staining for PAX-5 (B cells), myeloperoxidase (MPO) (myeloid cells), and CD3 (T cells) (56, –, 58)." (PMID 35852337, 2022). "Tumor cells can also produce high levels of H2O2, required for MPO driven homocitrullination, as a result of the oncogenic transformation associated with antioxidant imbalances." (PMID 35464453, 2022). "The release of neutrophil extracellular traps (NETs) containing HMGB1, neutrophil elastase, myeloperoxidase, and matrix metalloproteinases (MMP8/9) and activating the integrin signaling also promotes the proliferation of tumor cells." (PMID 35585567, 2022). "Neutrophils can release a series of proteins or chemokines, such as Neutrophil Elastase (NE), myeloperoxidase (MPO), cytokines, fibroblast growth factor-2 (FGF-2), matrix metalloproteinase-9 and VEGF to promote tumor proliferation, invasion and angiogenesis." (PMID 35317078, 2022). "NETs are comprised of MMPs, cathepsin G neutrophil elastase, and myeloperoxidase which induces the production of pro-inflammatory cytokines and orchestrates the TME, thereby enhancing tumor progression and metastasis." (PMID 35585567, 2022). "We also observed a similar immune cell infiltration profile in the A20 tumour model, where CAR(NAP) T-cell treatment led to higher infiltration of CD8+ T cells and Gr1+MPO+ neutrophils, and lower infiltration of FoxP3+CD4+ regulatory T cells." (PMID 35379957, 2022). "The majority of studies on individual cancer types used circulating markers, such as the MPO–DNA complex, as a NET marker, while in this study we used a pan-cancer tumor-infiltrated NET score derived from a broad data set." (PMID 35432310, 2022). "It decreased levels of the tumor (CEA and CA 19-9) and inflammatory (CRP and MPO) markers to normal levels in both of nano-extract simult- and post-treated groups." (PMID 34711004, 2021).
tumor (continued). "MPO-positive neutrophils were compared across these four groups, identifying significantly elevated neutrophil infiltration in SAAHIGHALOX5LOW tumours." (PMID 34203378, 2021). "Like histones, NE, and MPO in vitro, NET components destroy tumor cells and block tumor growth and metastasis formation." (PMID 34503307, 2021). "Next, we confirmed that NETosis was morphologically detectable in the tumor thrombus through testing positive for a DAPI, H3Cit, and MPO signal with IHC." (PMID 34993135, 2021). "In G-MDSC from peritoneum or spleen of the tumor mouse model, increased ARG 1 and MPO activity, higher ROS production, lower phagocytosis associated enzymes were found when compared to neutrophils from tumor-free mice." (PMID 34367125, 2021). "Immunostaining revealed many CD163‐positive TAMs (M2 macrophages), CD15, MPO‐positive TANs, and CD3, CD25‐positive Tregs in the tumor." (PMID 33174378, 2021). "In Cxcr2 knockout PKF (LSL-KrasG12D/+; Tgfbr2flox/flox, Ptf1a-Cre) mice, infiltration of myeloperoxidase+ (MPO+) neutrophils and CD11b+Ly6G+ MDSCs to tumor is decreased compared to control animals." (PMID 34439836, 2021). "On immunohistochemical analysis using anti-myeloperoxidase (MPO) antibodies, the tumor cells showed strong cytoplasmic reactivity." (PMID 34805008, 2021). "(E) Quantification of total CD45+ globoid cells and MPO+ neutrophils in the VI of WT and CCR2KO animals, 10 d.p.i. ***p<0.001, WT tumor vs. CCR2KO tumor in Bonferroni post hoc analysis in two-way ANOVA." (PMID 32391790, 2020). "(F) Representative images of a p63-positive PDA tumor stained with DAPI (blue), MPO (orange), αSMA (white), MUC1 (green), p63 (red), and overlaid (merge)." (PMID 32329713, 2020). "We used immunofluorescence analysis to quantify total CD45+ globoid cells and MPO+ cells in the VI in vehicle-, RS504393-, and SB225002-treated tumor-bearing animals." (PMID 32391790, 2020). "In contrast, most of the myeloperoxidase (MPO)-positive neutrophils, CD3-positive T cells, and CD45R-positive B cells were absent from the tumoral region but present exclusively in the non-tumor region." (PMID 32382012, 2020). "PDS reduced the spleen index but increased the thymus index in tumor-bearing mice and reduced the NEUT%, NLR, and MPO expression of tumor-bearing mice." (PMID 32015754, 2020). "Myeloperoxidase (MPO), complement C3, inter-alpha-trypsin inhibitor heavy chain H4 (ITIH4), apolipoprotein B-100 and kininogen-1 isoform 2 (KNG1) increased in the tumor group compared to the benign group." (PMID 32998289, 2020). "It restored levels of the tumor (CEA and CA 19-9) and inflammatory (C-RP and MPO) markers to normalcy in post-treated group." (PMID 32458646, 2020). "The immunohistochemical profile of the tumor cells was as follows: positive for CD45 and myeloperoxidase (MPO) on granulocyte." (PMID 31876710, 2019). "Tumor depths ranged from 1.2–6.8 mm, suggesting the efficacy of the CRET sensor for the monitoring of MPO in deep inflamed tissues." (PMID 31163706, 2019). "Immunohistochemical staining revealed that the large-sized tumor cells were positive for CD20, PAX-5, MUM-1 and BCL-2, and were negative for CD3, CD5, CD43, CD10, CD23, CyclinD1, CD138, CD30, ALK, CD56, MPO, S-100, TTF-1, thyroglobulin and calcitonin." (PMID 28841887, 2017). "Correlation of clinicopathological parameters with MPO and CD8 score according to different tumor compartments." (PMID 29085358, 2017). "This included TNF-α production, the synthesis of iNOS and MPO, and also the emergence of H2O2 within the tumor." (PMID 27806313, 2016). "In this study, we demonstrated that inhibition of MPO activity by a novel tripeptide inhibitor KYC in the MCA-initiated BHT-promoted model of lung carcinogenesis, reduced tumor burden by 50%." (PMID 24821130, 2014).
tumor (continued). "We used a multistage model of SCC to examine the involvement of elastase (ELA), myeloperoxidase (MPO), nitric oxide (NO), cytokines (IL-6, IL-10, IL-13, IL-17, TGF-β and TNF-α), and neutrophils and macrophages in tumour development." (PMID 23176085, 2012). "While verdiperstat is a selective MPO inhibitor and has no known off target effects, we also sought to confirm the decreased MPO activity was not simply due to a lack of MPO in the tumor microenvironment." (PMID 40797324, 2025). "CD11b was also expressed by neutrophils, which were present in tumours; hence, we confirmed that most of the CD11b+ cells at the tumour core were macrophages rather than MPO+ neutrophils." (PMID 40523200, 2025). "iNOS, myeloperoxidase (MPO), NADPH oxidase, and xanthine oxidase (XO), as well as upregulated cyclooxygenase 2 (COX2) and lipoxygenase (LOX), are just a few of the oxidant-producing enzymes that the inflammatory cells in the tumor microenvironment activate." (PMID 40801639, 2025). "Obese tumor-bearing mice had higher levels of NETs in circulation (estimated by analysis of dsDNA and citrullinated histone H3) and tumor tissue (immunohistochemical analysis using anti-PAD4, anti-MPO, anti-citrullinated histone H3, and anti-NE antibodies)." (PMID 39861371, 2025). "Given the MPO-specificity of L-012 and luminol, our data suggest a substantial presence of MPO-activated neutrophils within PDAC tumors, aligning with previous studies demonstrating that neutrophils comprise an abundant portion of the PDAC tumor microenvironment." (PMID 41462673, 2025). "Compared to APCP, PPCP exhibited significantly lower PD-L1 (an immune checkpoint protein expressed on tumor cells) expression and higher expression levels of CD38 (an immunosuppressive marker), S100A8/A9 (a neutrophil marker), and MPO (myeloperoxidase, a neutrophil marker)." (PMID 40721446, 2025). "Production of ROS, MPO, and H2O2 mediate the direct cytotoxicity of tumor cells by neutrophils." (PMID 39801751, 2025). "The same conclusion could be observed from the mIHC staining of MPO, NE, and CD8 based on the same samples of tumor tissue." (PMID 40305734, 2025). "Our study provides novel insights into the role of neutrophils in CRC progression, particularly through MPO and FCGR1A, which may serve as critical markers in understanding immune-medicated tumor progression." (PMID 40003985, 2025). "Our previous results have demonstrated that CAMP attachment to NE significantly increases the release of myeloperoxidase (MPO) and tumor necrosis factor (TNF)‐α compared with untreated NEs showing activation and a shift towards anti‐tumor N1 phenotype in vitro." (PMID 39801750, 2025). "This pattern indicates that neutrophils are not uniformly distributed across the tumor tissue, with certain regions showing a higher density of Ly6G+ and MPO+ cells." (PMID 39971940, 2025). "In addition, MPO secreted by TANs can catalyze the production of hypochlorous acid (HOCl) from H2O2 and Cl−, which directly oxidizes tumor cell membrane lipids, resulting in a 4-fold increase in lipid peroxidation and accelerating the ferroptosis process." (PMID 40535125, 2025). "Further supporting this potential conserved relationship, analysis of the GSE54129 dataset (containing mixed normal and tumor samples) revealed a significant negative correlation between MPO levels and pepsinogen A (PGA) expression (r = -0.187, p < 0.05)." (PMID 40547041, 2025). "IHC staining results showed that I-MMAE and I-DXd potently eliminated tumor-infiltrating TANs in TME at both total TANs (Ly6G+) and pro-tumor TANs (MPO+) levels, and I-DXd reached a superior TAN elimination rate than I-MMAE, as high as 75% for total TANs and 85% for pro-tumor TANs, respectively." (PMID 39971940, 2025). "Moreover, neutrophils infiltrating the lung tumor microenvironment express high levels of MPO, which suppresses the anti-tumor functions of both CD4+ and CD8+ T cells and promotes tumor progression." (PMID 41254689, 2025).
tumor (continued). "As MPO was not expressed on tumor cells, it was classified as neutrophil marker in both the parenchyma and stroma." (PMID 40721446, 2025). "The mechanisms linking these novel inflammatory markers, such as MPO, high-sensitivity troponin, and hs-CRP, and anti-tumor therapy-associated cardiovascular toxicity has not been fully investigated." (PMID 40182041, 2025). "We also propose the therapeutic significance of streptococcal collagen-like-1 (Scl1) protein as an essential factor in GAS anti-tumor response that supports tumor colonization, and acts as a potent inhibitor of NET activity through reduction of myeloperoxidase activity." (PMID 38515758, 2024). "In the coculture containing LN229TAZ(4SA) cells and dHL-60 neutrophils, MPO-immune-gold particles were found in isolated neutrophils, but not in tumor cells when they have no internalized dHL-60 cells." (PMID 38806658, 2024). "By quantifying and comparing Bcl-xL expression levels in MPO-positive cells in tumors and tumor-adjacent non-cancerous tissue, we demonstrated that TANs express significantly more Bcl-xL compared to peritumoral neutrophils." (PMID 38177532, 2024). "Multiple MET markers (CitH3, MPO, MMP2, MMP9, and MMP12) were elevated in macrophages that were co-cultured with tumour cells, but this effect could be rescued by treatment with MET inhibitor (Cl-amidine, a specific PADI4 inhibitor) or GW." (PMID 39025845, 2024). "In the METTL5‐sh group, MPO and H3 expression were lower than negative control group in subcutaneous tumor tissue sections of nude mice derived from either SMMC‐7721 or HepG2 cell lines." (PMID 38613157, 2024). "Our data also suggest that MPO does not contribute to the infiltration of CD8+ T cells within the tumor microenvironment." (PMID 38367056, 2024). "Papilloma induced by topical treatment of susceptible mice with 7, 12-dimethylbenz[α]anthracene (DMBA) and 12-O-tetradecanoyl phorbol-13-acetate (TPA) contained substantial numbers of MPO+ CXCR2+ Gr1+ MDSCs, and CXCR2 KO mice were profoundly resistant to the tumor induction." (PMID 38786066, 2024). "The quantification and colocalization of MPO activity and ROS levels using luminol and L-012 primarily reflects the contribution of infiltrating immune cells rather than the tumor cells themselves." (PMID 38367056, 2024). "Both neutrophils and MDSCs isolated from tumor-bearing WT mice had statistically significant increase in suppression of CD8+ T cell proliferation compared to neutrophils and MDSCs isolated from tumor-bearing MPO−/− and healthy WT mice." (PMID 38367056, 2024). "Importantly, our study is the first to demonstrate that targeted MPO inhibition, using 4‐ABAH as a single agent, significantly reduced MM tumour burden in the 5TGM1‐KaLwRij mouse model." (PMID 37699574, 2023). "Traditionally MPO inhibitors have been used to treat tumors without RT, but this suggests that high MPO activity is required to maintain the anti-tumor response of TANs after RT." (PMID 37833255, 2023). "Interestingly, MPO directly influenced CD8+ T-cell function in vitro and in vivo, thereby affecting tumour development." (PMID 37627581, 2023). "Then, we performed immunofluorescence staining on the normal lung, primary tumor, and metastatic lung sections using the markers of Tppp3+ monocytes (LY6C and TPPP3), Isg15+ macrophages (F4/80 and ISG15), Ifit3+ neutrophils (MPO and IFIT3), and Il12b+ DCs (CD11c and IL12B)." (PMID 37483625, 2023). "Myeloperoxidase oxidizes 3-IAA, which, through a series of enzymatic reactions, leads to ROS accumulation in vivo and down-regulation of tumor cell autophagy, thereby inhibiting tumor cell proliferation." (PMID 38169949, 2023). "The leukemic cells of the other six PML::RARA-negative AML cases with APL-like morphological features, except the KMT2A-positive patient (due to the specific tumor biology), had more or less a typical myeloid immunophenotype, with strong expression of pan-myeloid antigens (CD33, CD13, MPO)." (PMID 36980947, 2023).
tumor (continued). "Importantly, targeting MPO with the potent irreversible inhibitor, 4‐aminobenzoic acid hydrazide (4‐ABAH), significantly reduced MM tumour burden in the 5TGM1‐KaLwRij mouse model of MM." (PMID 37699574, 2023). "Coupled with the observation that MPO activity is co‐localised at sites of MM tumour development, these data suggest that MDSC may represent a major source of MPO in the context of MM." (PMID 37699574, 2023). "Given the crucial role of neutrophil-derived MPO in the release of toxic 3-IAA products, we wondered whether this could explain the increased efficacy of 3-IAA and FIRINOX on tumour growth." (PMID 36813961, 2023). "One recent study explored the relationship between tumor-associated neutrophils and outcomes in anal SCC using myeloperoxidase (MPO) as a marker, and found that neutrophils were not related to treatment outcome." (PMID 35751111, 2022). "Beyond those metabolic, pro-inflammatory and oncogenic changes, tumor-bearing HFD-fed obese mice displayed higher contents of circulating dsDNA and citrullinated histone H3, as well as tumor immunopositivity of citrullinated histone H3, neutrophil elastase, PAD4 and MPO." (PMID 36012397, 2022). "Tumor tissue is inflamed and granulocyte-rich as expected, the immunohistochemical positivity of MPO is much higher in tumor tissues than that in their matched adjacent non-cancerous tissues." (PMID 35912260, 2022). "While EPX is the only peroxidase present in eosinophil granules, we wanted to confirm that peroxidase activity derived from co-cultures of tumor cells and negatively selected eosinophils was not potentially due to neutrophil-derived myeloperoxidase." (PMID 35756626, 2022). "The tumor + probiotics group had a lower percentage of MPO positive cells; however, the difference was not significant." (PMID 35887022, 2022). "Both CTx groups had a significantly lower tumor infiltration with MPO positive cells when compared to both groups that did not receive CTx." (PMID 35887022, 2022). "The markers used to identify TANs, including CD66b and myeloperoxidase (MPO), may explain these discrepancies, since the expression of these markers on neutrophils may vary in different tumor microenvironments." (PMID 35386697, 2022). "Herein, tumor growth between HFD-fed obese and ND-fed lean mice was closely related to elevated circulating WBCs, lymphocytes, neutrophils, plasma levels of soluble P-selectin, TGF-β1 and HMGB1, as well as increased tumor expressions of HMGB1, RAGE, Smad2/3 phosphorylation, CD62P and MPO." (PMID 36012397, 2022). "Of note, despite inducing phenotypic activation, apoptotic tumour cell-CM failed to stimulate myeloperoxidase release, which is considered a typical pro-inflammatory neutrophil response." (PMID 35121727, 2022). "Some tumor cells were positive for CD68, a marker associated with the myeloid lineage, but were negative for myeloperoxidase (MPO) and terminal deoxynucleotidyl transferase." (PMID 36316914, 2022). "Our data showed that lack of IL-1B resulted in increased primary tumour growth and decreased infiltration of MPO+ neutrophils and F4/80+ macrophages." (PMID 34290237, 2021). "Pharmacological blockade of IL‐1 receptor (IL‐1R) decreased the primary growth of 4T1 tumours and reduced the systemic levels of myeloperoxidase, cell‐free DNA (cfDNA) and G‐CSF, without interfering with neutrophil counts." (PMID 33955688, 2021). "A tumor biopsy was performed, and the histological findings of the tumor lesion showed a proliferation of tumor cells that were positive for myeloperoxidase and CD68 and negative for CD4 and CD123." (PMID 33976945, 2021). "In order to focus the analysis rigidly on defined individual signaling pathways, the tumor cells were confronted with exogenously added defined signaling compounds such as the NO donor DEA NONOate or MPO at the respective optimal cell density." (PMID 34679719, 2021).